ENSG00000200075
Synonyms: LOC124900265
Gene: Small nucleolar RNA gene on chromosome 8 (129,868,590 to 129,868,716, reverse strand). Ensembl gene ENSG00000200075.
Gene Ontology:
Biological process: RNA processing
Cellular component: nucleolus
Homologues: Orthologues: mouse Gm54926 (53% identical). Paralogues in human: SNORA25B (79% identical), SNORA25 (76% identical).